INS (insulin)
Diseases named in the same sentence as INS in open-access papers (continued):
Sharing a sentence is not in itself a finding about the gene and the disease.
type 2 diabetes (continued). "Plant-based diets almost immediately reduce the need for insulin in “insulin-dependent” type 2 diabetics, because absorption of complex carbohydrates from plants just modestly increases plasma glucose levels, which obviates the need for insulin to facilitate glucose storage." (PMID 29403436, 2017). "Herein we showed that exposition of mesenchymal stromal cells isolated from adipose tissue of patients with type 2 diabetes to bFGF in a dose of 5 ng/mL caused significant increase in the level of GLUT-4 gene and protein expression, suggesting enhanced insulin sensitivity of those cells." (PMID 28168007, 2017). "In high fat and fructose-induced Type 2 diabetic rats, ferulic acid restored normal glucose homeostasis, improving insulin sensitivity and hepatic glycogenesis and inhibiting gluconeogenesis and the expression of insulin signalling inhibitors, such as the gluconeogenic enzyme genes PEPCK and G6Pase." (PMID 28574454, 2017). "Magnesium supplementation can also improve insulin sensitivity even in normo-magnesemic, overweight subjects emphasizing the need for an early optimization of magnesium status to prevent IR and subsequently Type 2 diabetes." (PMID 28884000, 2017). "Gene set enrichment analysis (GSEA) identified enrichment (FDR-adjusted P-value <0.05) of insulin signaling, oxidative phosphorylation, maturity-onset diabetes of the young (MODY), and glycolysis/gluconeogenesis KEGG pathways in beta cells relative to the other endocrine cells." (PMID 27864352, 2017). "If the close relationship between insulin sensitivity and the QTc interval could be demonstrated, strategies targeting to improve insulin sensitivity may ameliorate the prolongation of the QTc interval and improve prognosis in type 2 diabetes patients." (PMID 28912840, 2017). "Secondly, hyperinsulinemia may also be a potential link between type 2 diabetes and cancer, as insulin is not only a metabolic hormone but also a growth factor that has anti-apoptotic and mitogenic effects via activation of the insulin receptor." (PMID 29238337, 2017). "Although many epidemiological studies have revealed that higher levels of CRF are associated with lower incidence of type 2 diabetes and better insulin sensitivity, the underling mechanisms have not been fully elucidated." (PMID 28278265, 2017). "The incidences of severe hypoglycemia events requiring emergency medical treatment were 0.115 events per person per year in type 1 diabetes, 0.118 in insulin-treated type 2 diabetes and 0.009 in people with type 2 diabetes taking sulfonylureas, with respective prevalence of 7.1%, 7.3%, and 0.8%." (PMID 28824815, 2017). "Yam powder, yam extract, and allantoin have been shown to improve B-cell function in maintaining insulin and glucose in a rat model of Type II diabetes, with antioxidative effects as well, improved lipid profiles, and increased release of glucagon-like peptide 1 (GLP1)." (PMID 29165314, 2017). "Also Oral Ascorbic acid supplementation ameliorates skeletal muscle oxidative stress during hyperinsulinemia and improves insulin-mediated glucose disposal in people with type 2 diabetes." (PMID 28807030, 2017). "Previous clinical studies found that plasma levels of IL-22 and the number of IL-22-producing CD4+ T cells were higher in insulin-resistant or type 2 diabetic obese individuals than in insulin-sensitive obese or lean individuals, but results were based on very small samples." (PMID 28143481, 2017). "Previous reports showed that vanadyl sulphate could markedly improve insulin sensitivity of muscle and liver in Type 2 diabetes human patients." (PMID 28072841, 2017). "This study showed that the presence of one or two A allele of the COMT Val108/158Met was associated with improved glycemic response, and with a better response to insulin detemir therapy in patients with type II diabetes, separating them as best candidates for detemir therapy." (PMID 29225702, 2017).
type 2 diabetes (continued). "In patients with type 2 diabetes who are receiving antidiabetic treatment, circulating nesfatin-1 levels are decreased, as antidiabetic treatments target the reduction of blood glucose, increased insulin sensitivity, and controlled food intake." (PMID 29445751, 2017). "That metformin could provide cardiovascular protection in insulin-treated individuals with type 2 diabetes provided proof of concept, albeit by extrapolation, for a similar effect in type 1 diabetes." (PMID 28770327, 2017). "Recently, a nested case–cohort study reported that an increased risk of type 2 diabetes is associated with early onset of menopause, but it did not adjust for potential intermediate risk factors such as glucose metabolism, insulin or shared genetic factors." (PMID 28721436, 2017). "Statins may increase the risk of new-onset diabetes and adversely affect glycaemic control, but their effects on the glycemic response and mortality outcomes following commencement of insulin therapy in patients with Type 2 Diabetes (T2D) are unclear." (PMID 28830436, 2017). "A simulated Mars mission over 105 days, as an example of extreme conditions pressuring the human organism, indicated that environmental stress would exert considerable metabolic stress, and space flight perturbations in insulin sensitivity led to subclinical type 2 diabetes-like symptoms." (PMID 29257069, 2017). "Elevated levels of fasting glucose and fasting insulin in non-diabetic individuals are markers of dysregulation of glucose metabolism and are strong risk factors for type 2 diabetes." (PMID 28905132, 2017). "A small double-blind placebo-controlled crossover trial conducted in the Netherlands, published in 2000, demonstrated reductions in HbA1c, weight and insulin dose requirement when metformin was added to treatment for 5 months in insulin-treated type 2 diabetes." (PMID 28770327, 2017). "Taking into consideration that hyperinsulinemia also occurs in the early phase of type 2 diabetes, and that insulin might affect cellular glucose metabolism, the effect of insulin on tenocytes in different glucose conditions was also examined." (PMID 28266660, 2017). "A dietary recommendation often proposed for patients suffering from type 2 diabetes is to ingest foods that do not cause an acute rise in insulin levels, therefore preventing over-stimulation of insulin secretion from the pancreas." (PMID 28555043, 2017). "Type 2 diabetes is characterized by decreased insulin sensitivity." (PMID 28272344, 2017). "Further analysis of the data and discussion for the implication of miR-195 in hepatic insulin signaling, glycogen synthesis, and the pathogenesis of type 2 diabetes are presented in "Saturated fatty acid-induced miR-195 impairs insulin signaling and glycogen metabolism in HepG2 cells"." (PMID 29159212, 2017). "We show that administration of SeP-neutralizing Ab could improve insulin secretion and glucose sensitivity in mouse models of type 2 diabetes." (PMID 29162828, 2017). "Experimental studies under laboratory conditions suggest that regular interruption of sitting using small bouts of walking may be effective in lowering glucose and insulin levels in healthy and overweight/obese adults and in individuals with type 2 diabetes." (PMID 27904925, 2017). "The goal of this post hoc analysis was to determine key patient and treatment-related factors impacting glycosylated hemoglobin (A1C) and hypoglycemia in patients with uncontrolled type 2 diabetes who were initiated to basal insulin (neutral protamine Hagedorn [NPH] or glargine)." (PMID 28151905, 2017). "It is important to note, however, that BMI was higher in participants with type 2 diabetes than in healthy participants; differences in fat mass could potentially influence insulin sensitivity and this should be kept in mind when interpreting these results." (PMID 28526920, 2017).
type 2 diabetes (continued). "It is speculated that the increasing burden of IFBG and type 2 diabetes in African migrants and urbanising Africa might be driven by environmental exposures that disturb the balance between beta cell function and insulin sensitivity." (PMID 28144712, 2017). "Of importance is that KCNQ1 overexpression may lead to decreased levels of insulin and development of type 2 diabetes." (PMID 29259974, 2017). "Therefore, FAM3B plays an important role in the progression of type 2 diabetes by negatively regulating islet function and insulin sensitivity in the liver." (PMID 28536423, 2017). "However, the current data reveal that SeP-neutralizing Ab ameliorates insulin secretion and hyperglycaemia in rodent models of type 2 diabetes." (PMID 29162828, 2017). "Although the impairment of insulin action – the interaction between insulin and peripheral tissues – is found in almost all type 2 diabetes patients, it is the impairment of insulin secretion that accounts for the development of hyperglycemia and the progression of the disease." (PMID 29214024, 2017). "Furthermore, a human study showed that exogenous growth hormone injection in the early evening decreased the metabolic clearance rate of insulin and reduced insulin sensitivity in subjects with type 2 diabetes." (PMID 28352282, 2017). "We hypothesized that prolonged consumption of CLW could enhance glucose homeostasis in a normal-weight insulin-insufficient animal model of type 2 diabetes." (PMID 29104217, 2017). "The expression of KCNQ1 has been found in the human pancreas and in a cultured, insulin-secreting cell line, but the role of Kv7.1 in the molecular pathogenesis of type 2 diabetes still remains unclear." (PMID 29259974, 2017). "Furthermore, many reports have indicated that pancreatic β cell mass is also decreased in type 2 diabetic patients with impaired insulin secretion." (PMID 28886131, 2017). "This expectation is consistent with the fact that the SVA-438 insertion is also linked to the risk allele (T) of the SNP rs6602203, which is associated with a reduced metabolic clearance rate of insulin (MCRI), an endophenotype that is associated with the risk of type 2 diabetes." (PMID 28824558, 2017). "Further research is needed to investigate whether intranasal application of insulin has similar effects on hypothalamic BOLD responses in patients with type 2 diabetes, and what the functional consequences are." (PMID 29042645, 2017). "Type 2 diabetes often presents impaired glucagon suppression by insulin and glucose." (PMID 28881681, 2017). "Several pharmacological treatments may be considered for type 2 diabetes, but some patients eventually require and benefit from insulin treatment." (PMID 28702259, 2017). "Therefore, ucOC should be considered as a potential agent to improve muscle glucose uptake in insulin resistant conditions including type 2 diabetes." (PMID 29204135, 2017). "Multiple studies have suggested that pioglitazone, a peroxisome proliferator-activated receptor γ (PPARγ) agonist, used as an insulin-sensitizing agent in the treatment of type 2 diabetes mellitus (T2DM), may have anti-atherosclerotic effects." (PMID 29037211, 2017). "In light of the current epidemic of type 2 diabetes, research aimed at understanding the interplay between intramyocellular lipid storage, mitochondrial energetics, and insulin action in skeletal muscle is of utmost importance for the development of new therapeutic strategies." (PMID 27981357, 2017). "Notably, clinical trials have demonstrated that recombinant human IGF-I administration can improve insulin sensitivity in type I or type II diabetes." (PMID 28209124, 2017). "Initially, fructose was a popular macronutrient choice for individuals with type 2 diabetes because fructose does not cause an acute rise in insulin due to the low glycemic index related to fructose." (PMID 28555043, 2017).
type 2 diabetes (continued). "Hence, present results indicate that A. lappa roots extract have improvement effects in type 2 diabetes complications through enhancement of beta cell function, induction of insulin sensitivity and insulin secretion, and reduction of insulin resistance index." (PMID 28348972, 2017). "Antioxidant therapies have been shown to reduce the oxidative stress, reduce susceptibility of low-density lipoprotein (LDL) to oxidation, inhibit secretion of pro-inflammatory cytokines, improve insulin signaling in vitro, and improve glycemic control in individuals with type 2 diabetes." (PMID 28613268, 2017). "In the 14 years between the two studies the proportion of people with type 2 diabetes treated with insulin had risen significantly from 11.7 to 18.7%, and the absolute number of severe hypoglycemia events had increased from 132 to an average of 191 events per year." (PMID 28824815, 2017). "Treatment with exogenous insulin is needed in people with type 1 and advanced type 2 diabetes." (PMID 28993722, 2017). "Elevated circulating levels of sFRP4 have also been observed several years before a diagnosis of type 2 diabetes, where it may play a critical role in linking islet inflammation with impaired insulin secretion." (PMID 28637297, 2017). "A meta-analysis of six RCTs demonstrated a significant reduction in FBG in 252 subjects with type 2 diabetes, however changes in HbA1c, inflammatory markers, fasting insulin and HOMA-IR were inconclusive, possibly due to the brief duration of the intervention (4–8 weeks)." (PMID 28475161, 2017). "In a group of sub-Saharan African patients with type 2 diabetes who were screened for diabetic retinopathy using angiography, we observed that those treated with insulin alone had higher rates and more severe forms of diabetic retinopathy than those on oral agents alone." (PMID 29017477, 2017). "In type 2 diabetes there are several quantitative and qualitative alterations of insulin secretion." (PMID 28589121, 2017). "Furthermore, the reduction of glucotoxicity with some glucose-lowering drugs restored the expression of incretin receptors in diabetic animals and improved incretin-induced insulin secretion in subjects with type 2 diabetes." (PMID 28626771, 2017). "Our results also lend further support to classical epidemiological studies showing an association between elevated circulating insulin and pancreatic cancer risk, especially in men, but little evidence for a role of type 2 diabetes." (PMID 28954281, 2017). "Therefore, in type 2 diabetes, combined intervention involving lipid-adjusting, uric acid-lowering, and insulin-sensitizing medication will more effectively lead to improvement in blood pressure, NAFLD, and glucose metabolism than either intervention alone." (PMID 28458689, 2017). "Therefore, we investigated the impact of insulin treatment on sarcopenia in patients with type 2 diabetes." (PMID 28246927, 2017). "Factors which decrease blood glucose concentrations following ingestion of a meal, independently of insulin, might help postpone insulin desensitization and slow the development of obesity and delay the onset of type-2 diabetes." (PMID 28819193, 2017). "However, normalisation of blood glucose levels, as clearly demonstrated in both (DAla2)GIP- and (DAla2)GIP/xenin-8-Gln-treated mice, has also been shown to independently restore GIP insulin-secretory function in type 2 diabetes." (PMID 28004148, 2017). "Our finding of obestatin’s stimulatory effect on insulin combined with the other beneficial effects of obestatin on β-cells, makes obestatin an extremely attractive multifunctional therapeutic candidate for Type 2 diabetes." (PMID 28428639, 2017). "In the normal non-transformed rat kidney cells that we used to represent the kidney as one of the major cancer target tissues in diabetes type II, we show here that several principles of molecular activity can be applied to ameliorate the genotoxicity of insulin." (PMID 29231877, 2017).
type 2 diabetes (continued). "Likewise, the treatment for Asian type 2 diabetic patients should be focused on multiple targets, including insulin sensitivity, β-cell mass and insulin secretion." (PMID 29104217, 2017). "This scenario may be analogous to leptin treatment in obesity and insulin treatment in type 2 diabetes, in which endogenous hormone resistance may limit efficacy and result in side effects." (PMID 28694840, 2017). "Secreted by adipocytes, the protein coding by RETN may link obesity to type II diabetes considering its functional biological functions on regulating insulin activity and biological source." (PMID 29258237, 2017). "These authors suggest that secreted insulin from the pancreas in the ZnT8 knock-out mouse suppresses hepatic insulin clearance and dysregulation of this process could play a role in the pathogenesis of type 2 diabetes." (PMID 29157234, 2017). "Indeed, it is possible that individuals with insulin-treated type 2 diabetes have been coded as E11+." (PMID 28314943, 2017). "Type 2 diabetes is a metabolic disorder resulting in altered protein, carbohydrate and fat metabolism and is characterized by impaired insulin secretion, impaired glucose and insulin homeostasis." (PMID 29125842, 2017). "BAT can modulate glucose and lipid homeostasis in addition to insulin stimulated glucose disposal, insulin sensitivity and diet induced thermogenesis with substantial benefits seen in the insulin sensitivity of Type 2 diabetics thus highlighting its potential clinical importance." (PMID 27865196, 2017). "Consistent with the previously reported ability of FGF21 administration to improve hyperglycaemia and enhance insulin sensitivity and glucose clearance, we observed a protection from type 2 diabetes and beta cell loss independent of body fat." (PMID 28770320, 2017). "RGZ is a synthetic PPARγ agonist, which has been used as an insulin sensitizer in Type 2 diabetes." (PMID 29201005, 2017). "An attractive implication of insulin signaling independent action of E4orf1 is that a drug based on E4orf1 action may be potentially beneficial for improving hyperglycemia in type 1 or type 2 diabetes." (PMID 27537838, 2016). "Consequently, impaired responsiveness to insulin, termed insulin resistance, is a key component of the metabolic syndrome and a prelude to type 2 diabetes mellitus (T2DM)." (PMID 26757949, 2016). "Thus, the pathological state of type 2 diabetes creates a situation in which glucose, insulin and plasma NEFA are elevated." (PMID 26864436, 2016). "Furthermore, we were unable to distinguish between insulin-dependent or Type I diabetes and Type II diabetes." (PMID 27711179, 2016). "Preliminary data from randomized trials comparing metformin to insulin in women with gestational diabetes and one small randomized trial in women with type 2 diabetes suggest metformin may have beneficial effects when added to insulin during pregnancy." (PMID 27435163, 2016). "Significantly increased urinary ACE2 levels were reported in insulin-resistant subjects with impaired fasting glucose, glucose intolerance, or type 2 diabetes, compared to subjects with normal glucose tolerance, suggesting a close link between ACE2 shedding and glucose control." (PMID 27313531, 2016). "Moreover the PREDIMED study has recently demonstrated that unsaturated fat can improve fasting insulin sensitivity and prevent the incidence of type 2 diabetes." (PMID 27537847, 2016). "However, when fuels such as glucose and FA are chronically elevated, as is the case in obesity and Type 2 diabetes, β-cells accumulate excess lipid that eventually impairs function, including insulin release." (PMID 27008626, 2016). "Several recent reports, however, suggest that when exercise is matched for total volume or energy expenditure, higher-intensity exercise training confers larger improvements in insulin sensitivity in individuals with obesity, metabolic syndrome and type 2 diabetes." (PMID 27115137, 2016).